RPL7A (ribosomal protein L7a)
Description:
Component of the large ribosomal subunit. The ribosome is a large ribonucleoprotein complex responsible for the synthesis of proteins in the cell.
Synonyms: SURF3; TRUP; L7A; eL8
Tractability: Small molecule: an approved drug acts on it; a structure with a bound ligand is known; a high-quality ligand is known. PROTAC: UniProt records ubiquitination sites on it; ubiquitination databases record sites on it; its protein half-life has been measured; a small molecule that binds it is known. Other modalities: a drug acting on it is in phase 2 or 3 trials.
Target class: Other cytosolic protein
Gene: Protein-coding gene on chromosome 9 (133,348,194 to 133,351,435, forward strand). Ensembl gene ENSG00000148303.
Subcellular location: Cytoplasm
Subcellular location (Human Protein Atlas): Nucleoli; Vesicles
Pathways (Reactome):
Metabolism of proteins: Eukaryotic Translation Termination; Formation of a pool of free 40S subunits; GTP hydrolysis and joining of the 60S ribosomal subunit; L13a-mediated translational silencing of Ceruloplasmin expression; PELO:HBS1L and ABCE1 dissociate a ribosome on a non-stop mRNA; Peptide chain elongation; Ribosome Quality Control (RQC) complex extracts and degrades nascent peptide; SRP-dependent cotranslational protein targeting to membrane; ZNF598 and the Ribosome-associated Quality Trigger (RQT) complex dissociate a ribosome stalled on a no-go mRNA
Metabolism of RNA: Major pathway of rRNA processing in the nucleolus and cytosol; Nonsense Mediated Decay (NMD) enhanced by the Exon Junction Complex (EJC); Nonsense Mediated Decay (NMD) independent of the Exon Junction Complex (EJC)
Cellular responses to stimuli: Response of EIF2AK4 (GCN2) to amino acid deficiency
Developmental Biology: Regulation of expression of SLITs and ROBOs
Disease: Viral mRNA Translation
Metabolism: Selenocysteine synthesis
Gene Ontology:
Molecular function: cadherin binding; protein binding; RNA binding; structural constituent of ribosome
Biological process: cytoplasmic translation; maturation of LSU-rRNA; negative regulation of myoblast fusion; spermatogenesis; striated muscle contraction; translation; ribosome biogenesis
Cellular component: cytoplasm; cytosolic large ribosomal subunit; cytosolic ribosome; focal adhesion; membrane; nucleolus; nucleus; ribosome; cytosol; ribonucleoprotein complex; synapse
Genetic constraint (gnomAD): Loss-of-function variants: 0 observed, 36.05 expected, observed/expected ratio (o/e) 0, 90% interval 0 to 0.083. The upper end of that interval is the gene's LOEUF score, 0.083, which puts it in group 1 of 6, group 1 being the genes least tolerant of losing a copy. Missense variants: 287 observed, 340.4 expected, observed/expected ratio (o/e) 0.84, 90% interval 0.76 to 0.93. Synonymous variants: 158 observed, 129.84 expected, observed/expected ratio (o/e) 1.22, 90% interval 1.07 to 1.39.
Homologues: Orthologues: dog RPL7A (100% identical), chimpanzee RPL7A (99% identical), mouse Rpl7a (99% identical), guinea pig RPL7A (98% identical), rat AABR07007121.1 (98% identical), rat AABR07072440.1 (94% identical), tropical clawed frog rpl7a (94% identical), Drosophila melanogaster RpL7A (68% identical), Caenorhabditis elegans rpl-7A (62% identical). Paralogues in human: RSL1D1 (24% identical), RPL10A (17% identical), NHP2 (16% identical).
Diseases named in the same sentence as RPL7A in open-access papers:
RPL7A is named in the same sentence as 23 diseases in open-access papers, as found by Europe PMC text mining. Sharing a sentence is not in itself a finding about the gene and the disease. The quoted sentences say what the papers report.
osteosarcoma (5 papers, 2018 to 2025). A usually aggressive malignant bone-forming mesenchymal neoplasm, predominantly affecting adolescents and young adults. "Low RPL7A expression is associated with elevated serum alkaline phosphatase (ALP) levels in osteosarcoma patients and serves as an independent predictor of poor prognosis in lung metastasis cases." (PMID 40831924, 2025). "In contrast, downregulation of RPL7A is associated with poor prognosis of overall survival of osteosarcoma patients with lung metastasis." (PMID 39165691, 2024). "Low levels of some ribosomal proteins might favor tumor growth, since RPL7A is strongly downregulated in osteosarcoma tissue compared to normal bone and low levels of RPL7A are associated with poor survival." (PMID 29662633, 2018). "Studies have found that the ribosomal protein RPL7A is significantly downregulated in osteosarcoma samples." (PMID 40831924, 2025).
breast carcinoma (2 papers, 2023 to 2025). "Analyzing the influence of ethanol in human breast cancer cells, another study showed that ethanol modulates the expression of RPL7A transcripts in a dose- and time-dependent manner, presumably through estrogen-responsive elements within the RPL7A promoter." (PMID 40940922, 2025).
colorectal cancer (1 paper, 2024). A primary or metastatic malignant neoplasm that affects the colon or rectum. "RPL7A has been found to be overexpressed in prostate and colorectal cancer." (PMID 39165691, 2024).
influenza (1 paper, 2025). An acute viral infection of the respiratory tract, occurring in isolated cases, in epidemics, or in pandemics; it is caused by serologically different strains of viruses (influenzaviruses) designated A, B, and C, has a 3-day incubation period, and usually lasts for 3 to 10 days. "For influenza, discriminatory ribosomal genes included RPL7A, RPL13, RPL18, RPL23A, RPLP2, RPS2, and RPS4X." (PMID 41020849, 2025).
injury (1 paper, 2024). Damage inflicted on the body as the direct or indirect result of an external force, with or without disruption of structural continuity. "Significantly, Rpl7a was identified as a hub gene in a murine model of traumatic brain injury, and increased Rps13 gene levels in microglia and epithelial cells were found to be aging-related in a single-cell sequence study on murine brains." (PMID 38590360, 2024).
larynx carcinoma (1 paper, 2010). A primary or metastatic malignant neoplasm involving the larynx. "A study of larynx carcinoma cells resistant to the drug taxol, which stalls cells in the G2/M phase of the cell cycle, were shown to have elevated levels of ribosomal protein L7a." (PMID 20955606, 2010).
Sepsis (1 paper, 2025). Sepsis is defined as life-threatening organ dysfunction caused by a dysregulated host response to infection. "Consistent with the role of IRAP in endosome recycling, we observed that RPL7a‐labeled ribosomes were partially enveloped within IRAP+ endosomes in platelets from mice subjected to sepsis." (PMID 39853919, 2025).
Tinnitus (1 paper, 2024). Tinnitus is an auditory perception that can be described as the experience of sound, in the ear or in the head, in the absence of external acoustic stimulation. "Rpl7a which encodes the ribosomal protein large subunit was found to be upregulated in the tinnitus group compared with the non-tinnitus group." (PMID 38562529, 2024). "However, Rpl7a was expressed at significantly higher levels in the tinnitus group than in the non-tinnitus group (p < 0.001) which was also true for the AC136661.1 (p < 0.05)." (PMID 38562529, 2024).
triple-negative breast carcinoma (1 paper, 2025). An invasive breast carcinoma which is negative for expression of estrogen receptor (ER), progesterone receptor (PR), and human epidermal growth factor receptor 2 (HER2). "Further supporting a role for RPL7a in cancer, another study using cannabidiol (CBD) identified key hub genes associated with triple negative breast cancer and RPL7A was among them." (PMID 40940922, 2025).
cancer (7 papers, 2016 to 2025). A tumor composed of atypical neoplastic, often pleomorphic cells that invade other tissues. "Many proteins such as RPL7A have increased expression in cancer." (PMID 35328027, 2022).
tumor (5 papers, 2008 to 2025). "Three of the identified proteins, RPL7a, RPL14, and RPS9, are ribosomal proteins involved in protein synthesis, control of cellular transformation, tumor growth, aggressiveness, and metastasis." (PMID 40229247, 2025).
infection (4 papers, 2011 to 2022). The state of being infected such as from the introduction of a foreign agent such as serum, vaccine, antigenic substance or organism. "Although the true receptor for RSV had not yet been identified, our results suggested that three ribosomal proteins (RPL5, RPL7a and RPL8) might play potential crucial roles in the infection and propagation of RSV in vector cells." (PMID 22028913, 2011).
RPL7A also shares sentences with these, for which no sentence is quoted: Age-related cataract (1 paper); bone marrow failure (1); colon cancer (1); depression (1); Diamond-Blackfan anemia (1); glioblastoma (1); invasive breast carcinoma (1); lymphoma (1); mantle cell lymphoma (1); multiple myeloma (1); ovarian carcinoma (1).